TNF (tumor necrosis factor)
Diseases named in the same sentence as TNF in open-access papers (continued):
Sharing a sentence is not in itself a finding about the gene and the disease.
interstitial cystitis (17 papers, 2013 to 2025). A rare chronic debilitating urogenital disease characterized by urinary frequency, urgency, and pelvic pain. "Members of the tumor necrosis factor (TNF) superfamily have been revealed to be associated with painful bladder syndrome/interstitial cystitis (PBS/IC)." (PMID 23251284, 2013). "JNK also has been previously documented to have a role in the development of inflammation in interstitial cystitis, since its activation enhances the release of IL-1β and TNF-α." (PMID 40426893, 2025). "At all experimental concentrations, it ameliorated interstitial cystitis symptoms by reducing bladder weight, vascular permeability, and expression levels of IL-6, TNF-α, TGF 1-β, and iNOS, while increasing SOD, CAT, and GSH levels." (PMID 37375759, 2023). "Urothelial cell apoptosis in patients with interstitial cystitis/bladder pain syndrome resulted from upregulation of the inflammatory signals, including p38 mitogen-activated protein kinase and tumor necrosis factor-α." (PMID 27249005, 2016). "Interstitial cystitis/painful bladder syndrome (IC/PBS) is characterized by increased bladder pain and urinary frequency and associated with increased IL-2, IL-6, IL-8, TNFα expression, and lowered levels of IL-4." (PMID 25962909, 2015). "Given the role of TNF-α in the physiopathology of interstitial cystitis, these results suggested that further studies are required to evaluate the potential use of strontium in the management of interstitial cystitis." (PMID 27355060, 2014). "Interstitial Cystitis or Bladder Pain Syndrome (IC/BPS) is a heterogeneous condition characterized by elevated levels of inflammatory cytokines, IL-1β, IL-6, IL-8, IL-10, TNF-α, and is associated with debilitating symptoms of pelvic pain and frequent urination." (PMID 33923265, 2021). "Another study's findings indicate that TNF-α mainly induces urothelium apoptosis via TRAIL pathway and TRAIL-R4 is the predominant receptor in the interstitial cystitis inflammation." (PMID 27355060, 2014). "In our interstitial cystitis model, created with lipopolysaccharide, SC did not make any significant changes in histopathology of the bladders and the levels of histamine; however, it significantly reduced the levels of TNF-α." (PMID 27355060, 2014). "Given the role of TNF-α in the physiopathology of interstitial cystitis, these results suggested that SC may be a promising agent for the treatment of IC/PBS and further studies are required to evaluate the potential use of strontium in the management of interstitial cystitis." (PMID 27355060, 2014).
lipodystrophy (17 papers, 2006 to 2025). A congenital or acquired disorder characterized by abnormal loss or redistribution of the adipose tissue in the body. "So far no report has yet to tie BSCL disorders to inflammation, although there was a report of elevated circulating TNFα (tumour necrosis factor α) levels in patients of HIV-associated lipodystrophy." (PMID 25195639, 2014). "In addition, IL-6 and TNF-α stimulates the hepatic lipogenesis and were also associated with lipodystrophy in HIV patients." (PMID 29997625, 2018). "Recently, PHID syndrome has also been associated with lipodystrophy, abnormal distribution of perivisceral fat, scleroderma-like skin modifications, and cardiomyopathy resulting from chronic inflammation, resistant to anti-TNF-α and anti-IL-1 therapy." (PMID 25132737, 2014). "ART, particularly protease inhibitors, exacerbates these issues by inducing lipodystrophy and increasing the production of inflammatory cytokines such as IL-6 and TNF-α." (PMID 39339002, 2024). "Here the authors describe a patient with inflammatory bowel disease and lipodystrophy, providing evidence that leptin aggravates intestinal inflammation with proinflammatory effects on leukocytes that are reversible by TNFα blockade." (PMID 31822667, 2019). "Though, in order to deepen our studies on the inflammatory profile of lipodystrophy we analyzed the plasma levels of cytokines involved in the development of IR such as IL-1β, IL-6 e TNF-α." (PMID 29449893, 2018). "Although preliminary, the authors speculated that lipodystrophy could be a result of elevated secretion of inflammatory cytokines IL-6 (interleukin-6) and TNFα." (PMID 25195639, 2014). "Our aim was to evaluate adipocyte-derived hormones (adiponectin, leptin, resistin, TNF-α, PAI-1) and ghrelin plasma levels and their relationship with IR in HIV-infected patients according to the presence of lipodystrophy and fat redistribution." (PMID 24958357, 2014). "This process is known to be enhanced by increased levels of tumor necrosis factor, interleukin 6 (IL-6), and hydroxycorticosteroids present in many patients with HIV lipodystrophy." (PMID 22046183, 2011). "Similarly, elevated circulating and mRNA levels of TNFα, IL-6 and MCP-1 in WAT and brown adipose tissue were found in a transgenic mouse model overexpressing nSREBP1c (nuclear SREBP1c) that mimics lipodystrophy." (PMID 25195639, 2014). "Higher serum TNF-α values were found among men without lipodystrophy compared to those with HALS." (PMID 34957175, 2021). "Regarding serum levels of adipocytokines and cytokines, when stratified by sex, a statistically significant difference was found only for TNF-α dosage among men, being higher among subjects without lipodystrophy, compared with men with a diagnosis of HALS (p = 0.0222)." (PMID 34957175, 2021). "In addition, tumor necrosis factor-α (TNFα) and nuclear transcription-factor sterol response element-binding protein 1c (SREBP1c) have also been shown to affect HIV-induced lipodystrophy, but confirmation is required in long-term prospective studies." (PMID 21939545, 2011).
malignant glioma (17 papers, 2006 to 2025). A grade III or grade IV glioma arising from the central nervous system. "In particular, αvβ3 integrin has been associated with angiogenesis in malignant gliomas via basic fibroblast growth factor (bFGF) and tumor necrosis factor α (TNF-α)." (PMID 34769082, 2021). "A previous study shows that TNF-α induces angiogenic factor upregulation in malignant glioma cells which play a role in RNA stabilization during GBM." (PMID 33643183, 2021). "For instance, our group recently reported that in the presence of malignant glioma cells, there is nearly complete abrogation of TNF-α and a significant upregulation of IL-10 secretion by stimulated naïve human monocytes in vitro." (PMID 23737783, 2013). "When human monocytes previously cultured with malignant glioma cells are co-cultured with naïve monocytes, naïve monocytes had a dramatically reduced ability to secrete TNF-α in response to stimulation." (PMID 23737783, 2013). "TNF-α has been reported to induce angiogenic factor up-regulation in malignant glioma cells which in turn promotes angiogenesis and tumour progression." (PMID 23905066, 2012). "In HeLa cells and human malignant glioma cells treated with tumor necrosis factor-α (TNF-α, which induces MTDH overexpression), MTDH translocates into the nucleus where it interacts with the p65 subunit of NF-κB and upregulates NF-κB-induced gene expression." (PMID 22768080, 2012). "For instance, it has been found that inhibition of NFκB activation confers sensitivity to TNF-α by impairment of cell cycle progression in six human malignant glioma cell lines." (PMID 23905066, 2012). "It was also demonstrated that MALAT1 overexpression promotes the malignant glioma phenotype by inducing epithelial–mesenchymal transition (EMT) and tumor necrosis factor (TNF) signaling through nuclear factor kappa B (NF-κB) activation." (PMID 36819921, 2023).
morbid obesity (17 papers, 2012 to 2026). An excess of body weight, normally defined as an individual with a body mass index greater than 35 or a body weight greater than one hundred percent of ideal body weight. "Patients in our study with morbid obesity, although associated with higher epicardial adipose tissue thickness, had lower serum TNF-α level than patients in the second group." (PMID 36984428, 2023). "We observed that leukocyte adhesion to human endothelial cells stimulated with TNFα was significantly higher in the morbid obesity than in the control group." (PMID 37124725, 2023). "A recent report examining visceral fat obtained from patients undergoing gastric bypass surgery for morbid obesity, has shown that calprotectin is generated by activated macrophages in visceral adipose tissue, possibly under the influence of TNF alpha." (PMID 31067253, 2019). "We detected that pre-stimulated HAEC monolayers with TNFα and the perfused with the diluted blood, increased leukocyte adhesion compared to vehicle in both groups but was significantly greater for patients with morbid obesity (p<0.0001)." (PMID 37124725, 2023). "This inflammation marker and TNFα were also increased in patients with morbid obesity." (PMID 34829944, 2021). "Adipokines such as leptin, TNFα and adiponectin have demonstrated cardiovascular activity with circulating leptin levels correlating with LV mass in morbid obesity and may also be responsible in contributing to the beneficial cardiac effects of bariatric surgery." (PMID 38007595, 2024). "In 70 Brazilian women with morbid obesity, the effect of genotype on the concentration of IL-6 but not TNF-α in the postprandial period was confirmed." (PMID 37626800, 2023).
Myalgia (17 papers, 2012 to 2025). "Increase in MCP-2 was specifically associated with subjective fever and chills, while CX3CL1 and TNF-α were associated with objective fever and myalgia." (PMID 38235127, 2023). "In addition to acting locally, TNF-α can enter the bloodstream and cause systemic effects such as stimulating the production of acute phase proteins by the liver, the release of adrenocorticotropic hormone, falling blood pressure, fever, myalgias, and others." (PMID 36432875, 2022). "Both types commonly present with fever, joint pain, and myalgia, but rashes are more frequent in anti-TNFα inhibitor-induced DIL, whereas serositis is more frequent in classical DIL." (PMID 39618753, 2024). "Interestingly, the distribution of the rs1800629 (TNF) polymorphism was similar between both arthralgia patients and control subjects, as well as between myalgia patients and control subjects, indicating that this polymorphism might not be associated with the pathophysiology of TMDp." (PMID 39201416, 2024). "Interleukin 6 (IL-6) and interleukin 8 (IL-8) levels increased in response to tooth clenching in both groups, while interleukin 7 (IL-7), interleukin 13 (IL-13) and tumor necrosis factor (TNF) rose only in patients with TMD-related myalgia." (PMID 37509035, 2023). "It was found that several serum pro-inflammatory cytokines, such as tumor necrosis factor (TNF)-α and interleukin, are involved in the generation of symptoms in FM, including sleep disturbances, fatigue, and myalgia." (PMID 34683021, 2021). "A moderate positive correlation was also observed between myalgias and the pro-inflammatory cytokine TNF-α." (PMID 25343623, 2014). "Some positive clinical correlations (weak to moderate) of interest need to be mentioned- IFN-γ and pain intensity, IFN-β, IL-1β individually and fatigue, TNF-α and headache, IL-4 and myalgia, IL-6 and skin rash." (PMID 25343623, 2014). "The accumulated IPP in monocytes and macrophages activates and proliferates γδ T cells, causing the release of pro-inflammatory cytokines TNFα and IL6, which can lead to an acute systemic inflammatory response, manifested as headaches, myalgia, flu-like symptoms." (PMID 39640483, 2024). "The main findings were that the masseter levels of IL-6, IL-7, IL-8 and IL-13 were higher in TMD myalgia patients than controls and that repetitive tooth-clenching increased the levels of IL-6 and IL-8 in both groups, while IL-7, IL-13 and TNF increased only in patients." (PMID 28243900, 2017). "The one subject who reported moderate myalgias and injection site pain after vaccination displayed a distinctive, early cytokine response profile which included IL‐6, IL‐2, IL‐8, IP‐10, MCP‐1, TNF‐α, TARC, and MCP‐4." (PMID 28991404, 2018). "Tooth-clenching increased IL-6, IL-7, IL-8, TNF and IL-13 in TMD myalgia patients and IL-6 and IL-8 in controls, in line with previous studies." (PMID 28243900, 2017). "In this study, we evaluated the activity of the neuroendocrine axes in patients with polymyalgia rheumatica (PMR) before and after tumor necrosis factor (TNF)-α-blocking etanercept treatment, which previously has been shown to reduce interleukin 6 (IL-6) and C-reactive protein (CRP) markedly in PMR." (PMID 22894827, 2012).
nosocomial infection (17 papers, 2016 to 2026). An infection acquired in a hospital or other healthcare setting. "We and others have repeatedly shown associations between reduction in the TNFα response and adverse outcomes including nosocomial infection, prolonged organ dysfunction, and death in critically ill children." (PMID 32887651, 2020). "In a previous study, TNFα response <200 pg/mL throughout 7 days after positive culture was associated with persistent nosocomial infection, while recovery above 200 pg/mL was associated with resolution of infection (p < 0.05)." (PMID 30455877, 2018). "Patients showing impaired TNF-α production in leukocytes upon ex vivo LPS stimulation have been reported to exhibit an increased risk of developing nosocomial infections." (PMID 29221433, 2017). "Stenotrophomonas maltophilia, a pathogen causing hospital-acquired infections, produces cytokines like IL-2, IFN-γ, and TNF-α, triggering systemic inflammation." (PMID 39483762, 2024). "SEB-based clustering, identified 3 severity-based groups of septic patients significantly different regarding mHLA-DR expression and TNFα level post-LPS, as well as 28-day mortality, and nosocomial infections." (PMID 32999313, 2020). "In addition, the circulating levels of five cytokines, IL-10, IL-15, IL-6, IL-8, and TNF alpha, were measured for each patient, and the results showed that patients with nosocomial infection had significantly increased IL-10 levels at RCC admission." (PMID 38426112, 2024). "We hypothesized that in a cohort of critically ill patients, those with a lower post-stimulation TNF-α level would have increased rates of nosocomial infections (NIs) and worse clinical outcomes." (PMID 32936371, 2020). "First, this study was a post-hoc analysis of a randomized controlled trial, meant to be hypothesis generating and was not specifically powered for the primary of outcome differences in nosocomial infections between tertiles of TNF-α response." (PMID 32936371, 2020). "We hypothesized that patients with a lower post-stimulation TNF-α level would have increased rates of nosocomial infections (NIs) and worse clinical outcomes." (PMID 30890150, 2019). "The lack of association between early LPS-induced TNF-α production and subsequent nosocomial infections is consistent with a previous study performed in critically ill adults." (PMID 27760554, 2016). "Critically ill pediatric patients with persistently low stimulated TNF-α production are more likely to acquire life-threatening infections, and treatment caused rapid improvement in stimulated TNF-α production, which was associated with the prevention of nosocomial infections." (PMID 29221433, 2017).
osteonecrosis (17 papers, 2014 to 2025). A none disease characterized by death of bone tissue due to a lack of blood supply. "It is generally accepted that apoptosis of osteocyte in necrotic zone caused by TNFα and its receptor is one of the main reasons resulted in osteonecrosis and the destruction of the bone structure." (PMID 30606261, 2019). "Apoptosis of osteocytes in the necrotic zone caused by TNFα and its receptor is one of the main reasons that resulted in the osteonecrosis and the destruction of bone structure." (PMID 30606261, 2019). "In fact, we demonstrate that TNFα-, IL-1α/β- or IL-6-deficient mice as well as wild-type mice administered a TNFα-inhibitor were significantly resistant to development of osteonecrosis accompanying infectious myelitis, even under bisphosphonate treatment." (PMID 28387378, 2017). "We observed that osteonecrosis promoted by infection was significantly blocked in TNFα-deficient mice." (PMID 28387378, 2017). "To determine whether TNFα is required for osteonecrosis development in our model system, we induced infectious osteomyelitis using a comparable experimental protocol in TNFα-deficient (TNFα KO) mice administered alendronate." (PMID 28387378, 2017). "Furthermore, SARS-CoV-2 infection causes an increase in inflammatory cytokines such as C-X-C motif–chemokine 10 (CXCL10), interferon gamma (IFN-γ), interleukins (ILs) 1 beta, 6, 8 and 17, and tumor necrosis factor alpha (TNF-α), resulting in bone mineral loss, osteonecrosis and chondrolysis." (PMID 36984576, 2023). "Restoration of butyrate through FMT or sodium butyrate supplementation alleviated osteonecrosis by modulating inflammatory cytokines, reducing TNF-α and IL-2, and increasing IL-4 expression." (PMID 40510588, 2025). "The increase in FGF-2 expression was observed to suppress TNF-α, a pro-inflammatory cytokine, thereby improving bone regeneration in a model of steroid-induced osteonecrosis." (PMID 39051378, 2024). "Several studies have indicated that increased TNF-α involves the progression of osteonecrosis of the femoral head the femoral head." (PMID 35035862, 2022). "TNFα has been previously reported to be elevated in serum and bone marrow in both animal and clinical experiments during the process of steroid-induced osteonecrosis." (PMID 30606261, 2019). "In order to investigate the involvement of TNFα in osteonecrosis, first, we measured and compared the content of TNFα in the necrotic zone and the adjacent normal zone of human femur head samples with ONFH." (PMID 30606261, 2019). "Produced mainly by macrophages as well as other immune cells, TNFα has been found elevated in serum and bone marrow in both animal and clinical experiments during the process of steroid-induced osteonecrosis." (PMID 30606261, 2019). "The blood chemistry data in the model group internal system revealed that the expression levels of both anti-and proinflammatory factors (IL-6, IL-10, and TNF-α) significantly increased after osteonecrosis induction, especially at 2 and 6 weeks." (PMID 28931847, 2017). "In the current study, the TLR4/NF-κB pathway and inflammation (IL-6, IL-10, and TNF-α) significantly increased after osteonecrosis induction by LPS with MPS." (PMID 28931847, 2017). "Level of ADAMTS-7 is elevated in articular cartilage of osteonecrosis of femoral head; ADMATS-7 is positively associated with TNF-α and NF-κB." (PMID 25653475, 2015). "It was also reported that TNF-a mediated inflammatory macrophage polarization might contribute to the pathogenesis of steroid-induced osteonecrosis." (PMID 35076564, 2022). "Instead, we show that osteonecrosis development in infectious osteomyelitis mice administered alendronate was significantly blocked by gene targeting of either TNFα-, IL-6 or IL-1α/β, or by treatment with a TNFα inhibitor." (PMID 28387378, 2017). "The authors suggest that the biologic therapy with an anti-TNF-α antibody might promote the manifestation of osteonecrosis and compromise oral healing capacity of the bone." (PMID 27088019, 2016).